CHST8 (carbohydrate sulfotransferase 8)
Description:
Catalyzes the transfer of sulfate to position 4 of non-reducing N-acetylgalactosamine (GalNAc) residues in both N-glycans and O-glycans. Transfers sulfate to the 4-position of GalNAc in the context of GalNAcbeta1->4GlcNAcbeta1->R attached to both N-linked and core 2 branched O-linked oligosaccharides. Required for biosynthesis of glycoprotein hormones lutropin and thyrotropin, by mediating sulfation of their carbohydrate structures. Not active toward chondroitin and dermatan.
Synonyms: GalNAc4ST-1; GALNAC4ST1; GalNAc4ST; PSS3
Tractability: Antibody: UniProt predicts a signal peptide or a membrane-spanning region.
Gene: Protein-coding gene on chromosome 19 (33,621,942 to 33,773,509, forward strand). Ensembl gene ENSG00000124302.
Subcellular location: Golgi apparatus membrane
Pathways (Reactome):
Metabolism of proteins: Reactions specific to the complex N-glycan synthesis pathway
Gene Ontology:
Molecular function: protein binding; sulfotransferase activity; dermatan 4-sulfotransferase activity
Biological process: hormone biosynthetic process; proteoglycan biosynthetic process; sulfur compound metabolic process; central nervous system development; carbohydrate biosynthetic process; glycoprotein biosynthetic process
Cellular component: Golgi membrane; membrane; Golgi apparatus
Genetic constraint (gnomAD): Loss-of-function variants: 13 observed, 20.66 expected, observed/expected ratio (o/e) 0.63, 90% interval 0.41 to 1. The upper end of that interval is the gene's LOEUF score, 1, which puts it in group 4 of 6, group 1 being the genes least tolerant of losing a copy. Missense variants: 634 observed, 611.87 expected, observed/expected ratio (o/e) 1.04, 90% interval 0.97 to 1.11. Synonymous variants: 259 observed, 260.5 expected, observed/expected ratio (o/e) 0.99, 90% interval 0.9 to 1.1.
Homologues: Orthologues: chimpanzee CHST8 (99% identical), macaque CHST8 (98% identical), pig CHST8 (90% identical), dog CHST8 (88% identical), guinea pig CHST8 (87% identical), mouse Chst8 (85% identical), rat Chst8 (85% identical), rabbit CHST8 (79% identical), tropical clawed frog kctd15 (62% identical), zebrafish CHST8 (53% identical). Paralogues in human: CHST9 (48% identical), CHST12 (30% identical), CHST11 (29% identical), CHST13 (28% identical), CHST14 (27% identical), CHST10 (25% identical).
Diseases named in the same sentence as CHST8 in open-access papers:
CHST8 is named in the same sentence as 9 diseases in open-access papers, as found by Europe PMC text mining. Sharing a sentence is not in itself a finding about the gene and the disease. The quoted sentences say what the papers report.
Obesity (5 papers, 2012 to 2020). Accumulation of substantial excess body fat. "The locus near rs2012033 was associated in both primary caries GWASs (dft p-value 8.21 × 10− 7; dfs p-value 1.40 × 10− 6) and harbored a candidate gene for hypodontia (CHST8) and a gene associated with obesity and preference for carbohydrate (KCTD15)." (PMID 31533690, 2019). "We found four strains with lower metabolic rate that might predict obesity susceptibility, Pax5+/-, Chst8-/-, Tfap2b+/-, and Pald1-/-." (PMID 32356724, 2020). "Strains with lower metabolic rate which might contribute to development of obesity include Chst8, Pax5, Pald1, and Tfap2b." (PMID 32356724, 2020). "Furthermore, changes in CpG methylation were observed in genes that are related to obesity and metabolism, including fat mass and obesity associated protein (FTO), carbohydrate sulfotransferase 8 (CHST8), and SH2 binding domain-containing protein 1 (SH2B1)." (PMID 30050001, 2018). "Instead, our screen suggests that different nearby cis gene may be more fruitful for further functional follow up for obesity, namely ZCCHC8, VPS33A, RSRC2; SPDEF, NUDT3; SETD1, VKORC1; SGSM2, SRR; VASP, SIX5; OTX1; BANK1; ARIH1; ELL; CHST8, respectively." (PMID 29608557, 2018).
peeling skin syndrome (1 paper, 2022). Peeling skin syndrome (PSS) refers to a group of rare autosomal recessive forms of ichthyosis that is characterized clinically by superficial, asymptomatic, spontaneous peeling of the skin and histologically by a shedding of the outer layers of the epidermis. "Interestingly, an allelic variant of a Chst8 exon has been involved in a peeling skin syndrome (OMIM #616265), highlighting the importance of a controlled Chst8 gene response." (PMID 35672304, 2022).
prion disease (1 paper, 2019). A transmissible disease that is caused by a protein that is able to induce abnormal folding of normal cellular proteins, leading to characteristic spongiform brain changes, which are associated with neuronal loss without an inflammatory response. "Carbohydrate sulfotransferase 8 (CHST8) expression, previously reported to be altered in prion diseases, was also examined." (PMID 30608949, 2019).
schizophrenia (1 paper, 2024). A major psychotic disorder characterized by abnormalities in the perception or expression of reality. "Furthermore, our transcriptome analysis identified significant genes, including FOXP1 and CHST8, providing insights into the molecular mechanisms underlying ECM changes in schizophrenia." (PMID 38491019, 2024).
tumor (1 paper, 2025). "Tumor cells expressing CHST8 were shown to suppress T-cell activation and loss of CHST8 attenuated tumor growth in a syngeneic mouse model." (PMID 41244914, 2025). "Moreover, CHST8 is involved in the sulfation of PD-L1 and its homologs, contributing to the enrichment of M2-type macrophages in the tumor microenvironment." (PMID 41244914, 2025).
CHST8 also shares sentences with these, for which no sentence is quoted: acral peeling skin syndrome (1 paper); Cognitive impairment (1); Hypodontia (1); lymphoma (1).